FOLR1 (folate receptor alpha)
Description:
Binds to folate and reduced folic acid derivatives and mediates delivery of 5-methyltetrahydrofolate and folate analogs into the interior of cells. Has high affinity for folate and folic acid analogs at neutral pH. Exposure to slightly acidic pH after receptor endocytosis triggers a conformation change that strongly reduces its affinity for folates and mediates their release. Required for normal embryonic development and normal cell proliferation (By similarity).
Synonyms: FR-alpha; FBP; FOLR; FRα; FRalpha; NCFTD
Tractability: Small molecule: a structure with a bound ligand is known; a high-quality ligand is known. Antibody: a drug acting on it is in phase 2 or 3 trials; UniProt places it where antibodies can reach, with high confidence; UniProt predicts a signal peptide or a membrane-spanning region; its Gene Ontology location is reachable by antibodies, with medium confidence. PROTAC: a small molecule that binds it is known. Other modalities: an approved drug acts on it.
Target class: Membrane receptor
Chemical probes: CHEMBL3335604, PD081588, PD081625, PD081815, PD082335, PD082379, PD083274, PD083779, PD085207
Gene: Protein-coding gene on chromosome 11 (72,189,558 to 72,196,323, forward strand). Ensembl gene ENSG00000110195.
Subcellular location: Cell membrane; Apical cell membrane; Basolateral cell membrane; Secreted; Cytoplasmic vesicle; Cytoplasmic vesicle, clathrin-coated vesicle; Endosome
Pathways (Reactome):
Vesicle-mediated transport: COPI-mediated anterograde transport; COPII-mediated vesicle transport; Cargo concentration in the ER
Gene Ontology:
Molecular function: folic acid binding; folic acid receptor activity; protein binding; signaling receptor activity
Biological process: cellular response to folic acid; folic acid transport; anterior neural tube closure; axon regeneration; cardiac neural crest cell migration involved in outflow tract morphogenesis; heart looping; neural crest cell migration involved in heart formation; pharyngeal arch artery morphogenesis; receptor-mediated endocytosis; regulation of canonical Wnt signaling pathway; regulation of transforming growth factor beta receptor signaling pathway; response to axon injury; tetrahydrofolate biosynthetic process
Cellular component: apical plasma membrane; basolateral plasma membrane; cell surface; cytoplasmic vesicle; endosome; external side of plasma membrane; extracellular exosome; nucleus; plasma membrane; endoplasmic reticulum membrane; endoplasmic reticulum-Golgi intermediate compartment membrane; ER to Golgi transport vesicle membrane; Golgi membrane; membrane; transport vesicle; brush border membrane; clathrin-coated vesicle; extracellular region
Genetic constraint (gnomAD): Loss-of-function variants: 11 observed, 24.77 expected, observed/expected ratio (o/e) 0.44, 90% interval 0.28 to 0.74. The upper end of that interval is the gene's LOEUF score, 0.74, which puts it in group 3 of 6, group 1 being the genes least tolerant of losing a copy. Missense variants: 273 observed, 336.83 expected, observed/expected ratio (o/e) 0.81, 90% interval 0.73 to 0.9. Synonymous variants: 108 observed, 123.14 expected, observed/expected ratio (o/e) 0.88, 90% interval 0.75 to 1.03.
Gene-disease validity (ClinGen):
ClinGen rates the evidence that FOLR1 causes each of these diseases.
neurodegenerative syndrome due to cerebral folate transport deficiency (autosomal recessive): Definitive.
Homologues: Orthologues: chimpanzee FOLR1 (99% identical), macaque FOLR1 (97% identical), zebrafish folr (47% identical), tropical clawed frog folr1 (46% identical). Paralogues in human: FOLR2 (72% identical), FOLR3 (68% identical), IZUMO1R (54% identical), RTBDN (16% identical).
Diseases named in the same sentence as FOLR1 in open-access papers:
FOLR1 is named in the same sentence as 174 diseases in open-access papers, as found by Europe PMC text mining. Sharing a sentence is not in itself a finding about the gene and the disease. The quoted sentences say what the papers report.
ovarian carcinoma (193 papers, 1993 to 2026). A malignant neoplasm originating from the surface ovarian epithelium. "This is achieved using a scFv derived from the MOv18 monoclonal antibody, which specifically binds to folate receptor alpha (FRα), a tumor-associated antigen overexpressed in many ovarian carcinoma cells." (PMID 40771804, 2025). "We confirmed folate receptor 1 (FOLR1) as a promising tumor-associated antigen in ovarian cancer patient samples." (PMID 38254822, 2024). "We confirmed high and consistent expressions of the tumor-associated antigen FOLR1 on primary ovarian cancer samples." (PMID 38254822, 2024). "FOLR1 (encoding FRα) was highly expressed in human ovarian cancer cell lines and ovarian cancer specimens, compared to other cell lines and cancers." (PMID 36402875, 2023). "Folate receptor alpha (FRα) is an example of a widely studied tumour-associated molecular target, which is overexpressed in up to 90% of epithelial ovarian cancers (EOC), among others." (PMID 34888759, 2023). "MOv18-IgE is directed against the tumour-associated antigen folate receptor alpha (FRα), which is expressed in upwards of 70% of ovarian carcinomas, as well as other tumour types." (PMID 34503270, 2021). "Decreased expression of FOLR1 in ovarian cancer cells is significantly associated with drug resistance." (PMID 29433550, 2018). "One group reported that FOLR1 expression in ovarian cancer negatively correlated with the loss of the potential tumor suppressor gene caveolin." (PMID 29433550, 2018). "Recently, it was shown that FOLR1 can be exploited for specific delivery of drugs linked to folic acid into ovarian cancer cells." (PMID 27485273, 2016). "Certainly, in depth investigations are requested to confirm These Data to elucidate the underlined molecular mechanism connecting FOLR1 expression to the global methylation status of ovarian cancers." (PMID 27485273, 2016). "In addition, even though low-grade ovarian carcinomas are less associated with FRα overexpression, 21% in our cohort presented with high mRNA FOLR1 expression." (PMID 39596024, 2024). "Another goal of our work was to investigate whether FOLR1 expression is associated with the degree of global DNA hypomethylation, which is considered to be a sign of unfavourable prognosis in ovarian cancer." (PMID 27485273, 2016). "As folate is an indirect supplier of methyl groups for general methylation processes in cells, one other aim of this work was to examine whether mRNA expression of FOLR1 was associated with the degree of global DNA methylation in ovarian cancer cells." (PMID 27485273, 2016). "ADCs directed against tissue factor (TF) and folate receptor alpha have shown effectiveness in platinum-resistant cervical and ovarian cancers." (PMID 41626151, 2026). "Mirvetuximab soravtansine (MIRV) is a first-in-class antibody-drug conjugate targeting folate receptor alpha (FRα), which is highly expressed in a substantial proportion of epithelial ovarian cancers." (PMID 42287581, 2026). "HER3 and folate receptor alpha (FOLR1) have promising prognostic biomarkers in ovarian cancer; however, the combined biological and prognostic impact of these two molecules has not yet been clearly demonstrated." (PMID 41901574, 2026). "CA125 and HE4 are currently used in clinical practice, whereas FOLR1 and MUC1 show promise as diagnostic and therapeutic targets for ovarian cancer." (PMID 40801326, 2025). "In this study, we conducted a large quality assessment to examine how well different laboratories and methods can detect folate receptor alpha in ovarian cancer samples." (PMID 41301065, 2025). "Consistent with this view, multiple clinical trials with second-generation ADCs targeting FOLR1 in ovarian cancer patients are currently ongoing (Sutro Biopharma, Inc., San Francisco, CA, USA)." (PMID 40507303, 2025). "As such, FOLR1-targeted therapies are under current investigation for these malignancies, with many studies focused on ovarian cancer." (PMID 40919994, 2025).
ovarian carcinoma (continued). "Farletuzumab has been previously reported to have specific, high-affinity binding to FOLR1, resulting in decreased cell growth and increased complement-mediated cytotoxicity in testing against ovarian cancer." (PMID 40919994, 2025). "We discovered that FOLR1 was predominantly expressed in epithelial ovarian cancer cells, with similar expression levels observed in both primary ovarian tumors and metastatic omental tumors from patients with high-grade serous ovarian cancer (HGSC)." (PMID 40029935, 2025). "Targeting folate receptor-alpha (FRα), a cell surface protein overexpressed in many ovarian cancers, has shown promise." (PMID 40940995, 2025). "OTL38 is a fluorescent tracer designed by On Target Laboratories that binds to folate receptor-alpha (FRα), which is overexpressed in ovarian cancer." (PMID 39941778, 2025). "A true positive prediction involved combining mirvetuximab soravtansine (anti-FOLR1 + tubulin inhibitor) with bevacizumab (anti-VEGFA) in platinum-resistant ovarian cancer." (PMID 41149468, 2025). "Mirvetuximab soravtansine (MIRV) is an ADC targeting folate receptor alpha (FRα) that has shown promising efficacy as monotherapy in FRα-positive, platinum-resistant epithelial ovarian cancer (EOC), leading to its accelerated FDA approval." (PMID 41471096, 2025). "For cohort 2, CA125, HE4, and MUC1 were increased in early-stage ovarian cancer whereas FOLR1 was equivalent between early-stage ovarian cancer and controls." (PMID 40801326, 2025). "Collectively, these results suggest that IMGN853 induces late-stage autophagy in FOLR1+ ovarian cancer cells, which contributes to its inhibitory effects on HGSC tumor cells." (PMID 40029935, 2025). "Folate receptor alpha (FRα), overexpressed in 90% of ovarian cancers, has been targeted by second‐generation CAR‐NK92 cells, which exhibited strong cytotoxicity against FRα‐positive ovarian cancer cells." (PMID 40525700, 2025). "In contrast, the folate receptor alpha (FRα) is overexpressed directly on tumor cells in epithelial ovarian cancer, and its selective expression pattern has enabled the development of antibody–drug conjugates (ADCs) for targeted tumor cell elimination." (PMID 40963633, 2025). "This study assessed the interobserver agreement in the immunohistochemical (IHC) evaluation of folate receptor alpha (FRα) expression in ovarian cancer across a cohort of 12 pathologists reviewing 37 cases." (PMID 40869006, 2025). "Folate receptor alpha has emerged as a clinically relevant biomarker for the identification and selection of patients eligible for targeted therapy in ovarian cancer." (PMID 40508029, 2025). "We selected the tumor-specific antigen FOLR1, which is highly expressed in ovarian carcinoma, a tumor indication with a high medical need for new therapeutic approaches." (PMID 40755782, 2025). "The ADCs targeting folate receptor alpha (FRα) have emerged as a promising therapeutic strategy for ovarian cancer, particularly due to the high expression of FRα in tumor tissues." (PMID 41347223, 2025). "Epithelial ovarian cancer (EOC) specimens demonstrate a range of folate receptor alpha (FRα) immunohistochemical staining intensities, categorized as weak, moderate, or strong." (PMID 40508029, 2025). "We further evaluated FOLR1 expression in 40 additional ovarian cancer samples with various histologic subtypes (20 HGSC, 10 endometrioid, and 10 clear-cell cases) from patients undergoing treatment with IMGN853." (PMID 40029935, 2025). "Key targets for CAR-NK cells include mesothelin and folate receptor alpha (FRα), both of which are overexpressed in ovarian cancer." (PMID 40260240, 2025). "Mirvetuximab soravtansine, an ADC targeting folate receptor alpha (FRα), was recently approved for platinum-resistant ovarian cancer with high FRα expression." (PMID 41228293, 2025). "Folate receptor alpha (FRα) is overexpressed in most ovarian cancers, with an overexpression rate of 80–96% in serous epithelial ovarian cancer." (PMID 39857752, 2025).
ovarian carcinoma (continued). "The aim of this review is to provide an overview of folate receptor alpha (FRα) expression in ovarian cancer, with a particular focus on its immunohistochemical evaluation using the Ventana FOLR1 RxDx Assay." (PMID 40508029, 2025). "In ovarian cancer, specifically, folate receptor alpha has a role in the downregulation of the tumor suppressor caveolin-1 (cav-1), which is important for cell proliferation." (PMID 40507303, 2025). "Next, we analyzed the on-tumor binding profile of the anti-FOLR1 scFv-Fc fusion proteins using primary human ovarian cancer tissues." (PMID 39594628, 2024). "Here, we selected folate receptor 1 (FOLR1 or FRα) as the target antigen for the treatment of ovarian cancer." (PMID 39594628, 2024). "Folate receptor alpha (FOLR1), which is a glycosylphosphatidylinositol-anchored glycoprotein has emerged as a promising biomarker for the detection of ovarian cancer, exhibiting notable potential and versatility in clinical applications." (PMID 40836974, 2024). "The objective was to determine the correlation between FOLR1 expression and patient outcomes in breast cancer, lung cancer, endometrial cancer, and ovarian cancer." (PMID 38256120, 2024). "In our study, we confirmed that FOLR1 mRNA expression is correlated with protein expression in ovarian cancer cell lines and is high in cancer ovarian samples." (PMID 39596024, 2024). "FOLR1 mRNA expression was significantly correlated with protein expression in pan-cancer cell lines and ovarian cancer cell lines." (PMID 39596024, 2024). "Antibody–drug conjugates targeting folate receptor alpha (FRα) are a promising treatment for platinum-resistant ovarian cancer (OC) with high FRα expression." (PMID 39596024, 2024). "In contrast, the other reported fully human anti-FOLR1 scFv, C4, was exclusively tested for on-tumor reactivity on ovarian carcinoma by immunohistochemistry." (PMID 39594628, 2024). "CAR-CIK cells are engineered to recognize and attack tumor cells that express FOLR1 and effectively kill ovarian cancer cells in vitro and in vivo." (PMID 40836974, 2024). "For example, the expression of FOLR1 has been shown to be 100–300 times higher in breast, lung, kidney, and ovarian cancers when compared to healthy cells." (PMID 38212621, 2024). "Their study focused on 254 ovarian cancers only and used MethyLight PCR reaction covering 7 of these 11 CpG sites upstream of the transcription site of FOLR1." (PMID 39596024, 2024). "MIRV is the first FDA-approved ADC targeting FOLR1 for the treatment of platinum-resistant ovarian cancer." (PMID 40836974, 2024). "Serum analysis has revealed elevated levels of FOLR1 in patients with ovarian cancer compared to those with benign gynecological conditions and healthy controls." (PMID 40836974, 2024). "On the other hand, folate–miR-34a inhibited cell proliferation in breast, cervical, and ovarian cancer cells that highly express FOLR1, indicating its potential therapeutic applications for these FOLR1-expressing cancers." (PMID 38396800, 2024). "REFRaME-O1 (NCT05870748) is a two-part phase II trial evaluating the efficacy and safety of luveltamab tazevibulin in patients with relapsed platinum-resistant epithelial ovarian cancer expressing folate receptor alpha." (PMID 39590153, 2024). "Folate receptor alpha (FRα) has emerged as a promising target in the treatment of ovarian cancer, with farletuzumab, a humanized monoclonal antibody targeting FRα, showing potential in clinical settings." (PMID 39677200, 2024). "An additional protein that has been studied as a target for CAR-T cells is the folate receptor alpha (FRα), which has been shown to be expressed in at least half of ovarian cancers of a diverse range of phenotypes and of limited expression in healthy tissues." (PMID 37835509, 2023).
ovarian carcinoma (continued). "Having established high levels of FOLR1 gene expression in ovarian cancer, we evaluated FRα protein expression in normal tissues and ovarian tumours by immunohistochemistry (N = 142 normal tissues; N = 316 ovarian tumours)." (PMID 36402875, 2023). "Ovarian cancers frequently overexpress Folate Receptor alpha (FRα) and the soluble receptor (sFRα) is measurable in blood." (PMID 36402875, 2023). "We describe a rational design process to achieve highly stable liposomes that are targeted with folate to folate-receptor-alpha, which is known to be overexpressed on the surface of ovarian cancer cells." (PMID 36828860, 2023). "Folate receptor alpha (FRα), as it is specifically overexpressed by cancer cells from various origins, including ovarian cancer cells, is a good target to address photosensitizing molecules." (PMID 36015182, 2022). "This current agent is indicated for ovarian cancer because of the presence of folate receptor alpha on these cancer cells." (PMID 36494869, 2022). "The serum FOLR1 level was significantly elevated in ovarian cancer patients compared with healthy and benign tumor populations." (PMID 36233339, 2022). "For comparison, the high FOLR1 expressing ovarian carcinoma HeLa cell line displayed an average of ~450,000 molecules per cell when cultured on chip, confirming the difference observed in IHC between healthy and tumor cells." (PMID 34378534, 2021). "We then validated PAtrace in phantom, in vitro, and in vivo PA imaging environments for both spectral unmixing accuracy and targeting efficacy with a folate receptor alpha-positive (FRα+) ovarian cancer model." (PMID 34518530, 2021). "(D) High FOLR1 expression displayed in human ovarian carcinoma HeLa cell line for comparison to (E) histopathological staining of primary healthy human lung tissue for FOLR1." (PMID 34378534, 2021). "We then validated PAtrace in phantom, in vitro, and in vivo PA imaging environments for both spectral unmixing accuracy and targeting efficacy in a folate receptor alpha-positive ovarian cancer model." (PMID 34518530, 2021). "More recently, HAdV5 retargeted towards folate receptor alpha (FRα), which is highly expressed on ovarian cancer cells, was evaluated for virotherapy application." (PMID 34683878, 2021). "It was shown that a vaccine composed of monocyte-derived autologous Th17-inducing DCs pulsed with folate receptor alpha (FRα) epitopes was highly immunogenic and promoted the prolongation of the remission period in patients with ovarian cancer." (PMID 34631558, 2021). "Conversely, folate receptor alpha (FRα) is highly expressed on ovarian cancer cells, providing a compelling target for tumour selective delivery of virotherapies." (PMID 31902944, 2020). "Evidence indicates that ovarian cancer cells express higher folate receptor alpha (FRα) compared with other cells of the body." (PMID 33392094, 2020). "Retargeting HAdV vector tropism towards the folate receptor alpha (FRα) represents an excellent approach for treating ovarian cancer." (PMID 31902944, 2020). "The level of soluble FOLR1 is selectively higher in cancer patients, a prominent example being ovarian carcinoma, where FOLR1 is upregulated." (PMID 32503320, 2020). "Targeting shared antigens: Aberrant overexpression of the folate binding protein or folate receptor alpha (FRα) is observed in more than 80% of ovarian cancers." (PMID 32630708, 2020). "In previous studies, the tumour targets of ovarian cancer-specific fluorescence imaging included folate receptor alpha (FR-α), follicle-stimulating hormone receptor (FSHR), anti–human epidermal growth factor receptor 2 (HER2) and so on." (PMID 32252772, 2020). "While conventional v9 × Farl biAb bound both CD3+ FOLR1– human T-cell line Jurkat and FOLR1+ CD3– human ovarian cancer cell line IGROV-1 as determined by flow cytometry, v9 × h38C2 biAb only bound Jurkat cells." (PMID 31497024, 2019).